GMPR (guanosine monophosphate reductase)
Description:
Catalyzes the irreversible NADPH-dependent deamination of GMP to IMP. It functions in the conversion of nucleobase, nucleoside and nucleotide derivatives of G to A nucleotides, and in maintaining the intracellular balance of A and G nucleotides.
Synonyms: GMPR 1; GMPR1; hGMPR-I
Tractability: Small molecule: a structure with a bound ligand is known; it has a high-quality binding pocket. PROTAC: ubiquitination databases record sites on it; its protein half-life has been measured.
Gene: Protein-coding gene on chromosome 6 (16,238,555 to 16,295,923, forward strand). Ensembl gene ENSG00000137198.
Pathways (Reactome):
Developmental Biology: Regulation of MITF-M dependent genes involved in invasion
Metabolism: Purine salvage
Gene Ontology:
Molecular function: GMP reductase activity; protein binding; catalytic activity; oxidoreductase activity
Biological process: response to cold; nucleotide metabolic process; purine nucleotide metabolic process
Cellular component: cytosol; GMP reductase complex
Genetic constraint (gnomAD): Loss-of-function variants: 18 observed, 21.92 expected, observed/expected ratio (o/e) 0.82, 90% interval 0.57 to 1.22. The upper end of that interval is the gene's LOEUF score, 1.22, which puts it in group 5 of 6, group 1 being the genes least tolerant of losing a copy. Missense variants: 326 observed, 330.6 expected, observed/expected ratio (o/e) 0.99, 90% interval 0.9 to 1.08. Synonymous variants: 116 observed, 128.63 expected, observed/expected ratio (o/e) 0.9, 90% interval 0.77 to 1.05.
Homologues: Orthologues: chimpanzee GMPR (99% identical), macaque GMPR (98% identical), rabbit GMPR (97% identical), rat Gmpr (96% identical), guinea pig GMPR (96% identical), dog GMPR (95% identical), mouse Gmpr (95% identical), tropical clawed frog gmpr (83% identical), zebrafish gmpr (83% identical), pig GMPR (73% identical), Caenorhabditis elegans gmpr-1 (69% identical). Paralogues in human: GMPR2 (80% identical), IMPDH1 (32% identical), IMPDH2 (30% identical).
Diseases named in the same sentence as GMPR in open-access papers:
GMPR is named in the same sentence as 20 diseases in open-access papers, as found by Europe PMC text mining. Sharing a sentence is not in itself a finding about the gene and the disease. The quoted sentences say what the papers report.
melanoma (8 papers, 2014 to 2025). A malignant, usually aggressive tumor composed of atypical, neoplastic melanocytes. "In this study, GMPR is considered to be an oncogene, and some studies have found that GMPR is a new melanoma invasion inhibitor." (PMID 35433681, 2022). "Guanosine monophosphate reductase is involved in de novo purine biosynthesis and if the expression of guanosine monophosphate reductase is reduced, melanoma aggressiveness is enhanced." (PMID 32509589, 2020). "Decreasing intracellular GTP pools can limit melanoma cell's invasiveness as it was confirmed in invasive melanomas that guanosine monophosphate reductase is down-regulated." (PMID 32509589, 2020). "Multiple studies have shown that GMPR plays an important biological role in melanoma." (PMID 37946181, 2023). "In addition, maintaining an appropriate level of GMPR expression potential can inhibit the development of melanoma, making GMPR a potential target for the treatment of melanoma." (PMID 37946181, 2023). "GMPR can deplete cellular GTP level, an event linked to lower melanoma invasiveness." (PMID 29369499, 2018). "Recently, two interesting studies which would at least partly explain the exclusive role of MITF in lowering invasiveness have implicated the expression of guanosine monophosphate reductase (GMPR), an enzyme of guanylate metabolism, in the regulation of invasiveness in melanoma cells." (PMID 29369499, 2018). "We confirmed the expression patterns of CLN6, GMPR, AP1S2, and ITGA6 in melanoma cells using gene-specific primers by qRT-PCR." (PMID 40821828, 2025). "GMPR was found that it could downregulate GTP-bound Rho-GTPases and inhibited the further development of melanoma." (PMID 32953885, 2020). "Thus, decreased expression of guanosine monophosphate reductase (GMPR) increases guanosine triphosphate (GTP) levels, which drives melanoma invasion." (PMID 29257071, 2017).
Alzheimer disease (3 papers, 2018 to 2024). A progressive, neurodegenerative disease characterized by loss of function and death of nerve cells in several areas of the brain leading to loss of cognitive function such as memory and language. "Here, we highlighted the role of 3 genes (GPR88, GPNMB, and GMPR) showing higher expression in CM (FC > 4) and that could be interesting key players of CM since higher expression of them are also associated to Parkinson's and Alzheimer's diseases." (PMID 32801995, 2020). "GMPR is gradually increased in Alzheimer’s disease and has the potential as a therapeutic target." (PMID 39610928, 2024).
African trypanosomiasis (2 papers, 2016 to 2020). "Herein, we identified the GMPR in Trypanosoma brucei, a causative protozoan parasite of African trypanosomiasis, and found that the GMPR proteins were consistently localized to glycosomes in T. brucei bloodstream forms." (PMID 26731263, 2016).
ovarian carcinoma (2 papers, 2023 to 2025). A malignant neoplasm originating from the surface ovarian epithelium. "The current study developed a predictive model of CSOARG for prognosis in ovarian cancer using eight key genes (WNK1, ANGPTL4, AREG, IGF1, CXCL10, GMPR, FANCB, LYG1)." (PMID 40510161, 2025).
asthma (1 paper, 2022). "The AUC value of FKBP5 (AUC = 0.832), WNT5A (AUC = 0.813), TM4SF1 (AUC = 0.769), PDK4 (AUC = 0.753), EPAS1 (AUC = 0.748) and GMPR (AUC = 0.705) was more than 0.7, which suggesting higher diagnostic value for asthma." (PMID 36550577, 2022). "The ROC curves illustrated that FKBP5, WNT5A, PDK4, and GMPR had potential diagnostic value for asthma." (PMID 36550577, 2022). "FKBP5, WNT5A, TM4SF1, PDK4, EPAS1 and GMPR had potential diagnostic value for asthma." (PMID 36550577, 2022). "Among them, PDK4, FKBP5, ZBTB16, WNT5A, GMPR and WIF1 are reported to be associated with asthma in the previous researches." (PMID 36550577, 2022).
autoimmune disease (1 paper, 2024). A disorder resulting from loss of function or tissue destruction of an organ or multiple organs, arising from humoral or cellular immune responses of the individual to their own tissue constituents. "The relationship between GMPR, DNAH8, MCEMP1, and autoimmune diseases has not yet been reported." (PMID 38639399, 2024).
lung adenocarcinoma (1 paper, 2023). A carcinoma that arises from the lung and is characterized by the presence of malignant glandular epithelial cells. "In our study, GMPR was found to be downregulated in lung adenocarcinoma and was correlated with poor prognosis." (PMID 37946181, 2023). "Moreover, the elevated expression of GMPR in ODFRGs in lung adenocarcinoma reduces the proliferation, migration, and invasion of lung cancer cells." (PMID 37946181, 2023). "Furthermore, overexpression of GMPR significantly reduces the proliferation of lung adenocarcinoma cells in A549 and PC9 cell lines." (PMID 37946181, 2023). "The results showed that, compared with normal samples, GMPR was under-expressed in tumors, MRPL13 was overexpressed in lung adenocarcinoma, while the expression of MCFD2 and SALL2 between normal lung tissue and lung adenocarcinoma tissue was not different." (PMID 37946181, 2023).
Obesity (1 paper, 2013). Accumulation of substantial excess body fat. "Here we report a 6p deletion of about 1 Mb encompassing five genes (ATXN1, DTNBP1, JARID2, MYLIP and GMPR), identified in a patient with severe ID, hypotonia, brain anomalies, EEG abnormalities, macrosomia, obesity, and ASDs with associated hyperactivity and behavioral abnormalities." (PMID 23324214, 2013).
progressive external ophthalmoplegia (1 paper, 2024). A mitochondrial myopathy characterized by slowly progressive paralysis of the levator palpebrae, orbicularis oculi, and extraocular muscles. "Heterozygous mutation in GMPR is a pivotal but rare cause of progressive external ophthalmoplegia (PEO) and GMPR is the 19th locus for PEO." (PMID 39610928, 2024).
sarcoma (1 paper, 2026). A usually aggressive malignant neoplasm of the soft tissue or bone. "Among the enzymes analyzed, high expression of GMPR was associated significantly with improved overall survival of sarcoma patients (HR = 0.57, p = 0.006, log-rank p = 0.0053), suggesting a potential protective role of GMPR." (PMID 41522344, 2026).
infection (5 papers, 2009 to 2024). The state of being infected such as from the introduction of a foreign agent such as serum, vaccine, antigenic substance or organism. "In soybean, transcript levels of GmPR1‐like and GmPR genes may either decrease or increase in the susceptible soybean lines following infection." (PMID 32954627, 2021).
tumor (4 papers, 2023 to 2026). "Several of these genes, such as CMTR1, play critical roles in mRNA cap methylation and immune response regulation, while GMPR and MT-TL1 are involved in metabolic pathways essential for tumor growth." (PMID 40725410, 2025). "The four-gene signature (CLN6, GMPR, AP1S2, ITGA6) and their validated roles in proliferation/migration (e.g., CLN6 knockdown suppressing tumor growth) provide novel therapeutic targets." (PMID 40821828, 2025). "Guanosine monophosphate reductase (GMPR, LRT p value = 0.05 × 10−2) is another positively selected gene detected in long‐lived mammals, which is a potential tumor suppressor that inhibits the regulatory pathway in tumor cells." (PMID 37395176, 2023).
cancer (2 papers, 2016 to 2025). A tumor composed of atypical neoplastic, often pleomorphic cells that invade other tissues. "Several of these genes, such as CMTR1 and GMPR, have known roles in RNA modification and purine metabolism, respectively, processes that are commonly dysregulated in cancer, particularly in aggressive subtypes like GBM." (PMID 40725410, 2025). "GMPR acts as a central node linking metabolic and nucleotide regulatory elements crucial for maintaining the proliferative state of cancer cells." (PMID 40725410, 2025). "For example, while GMPR and ENPP1 interact simply through the KEGG purine metabolism pathway, the APC-FZD3 interaction involves three different pathways: KEGG basal carcinoma, KEGG pathways in cancer, and KEGG wnt signaling pathway." (PMID 27378931, 2016).
neurodegenerative disease (2 papers, 2015 to 2023). A disorder of the central nervous system characterized by gradual and progressive loss of neural tissue and neurologic function. "Other music-related genes (GMPR, SELENBP1 and ADIPOR1) associated to neuropsychiatric, neurodegenerative diseases and music performance, emerged as hub genes in consensus co-expression modules detected between AD and music estimulated transcriptomes." (PMID 36819725, 2023).
GMPR also shares sentences with these, for which no sentence is quoted: Parkinson's (2 papers); COVID-19 (1); cutaneous melanoma (1); developmental delays (1); External ophthalmoplegia (1); lung carcinoma (1).